INS (insulin)
Diseases named in the same sentence as INS in open-access papers (continued):
Sharing a sentence is not in itself a finding about the gene and the disease.
diabetes (continued). "Among the mechanisms of podocyte injury in diabetes, mitochondrial dysfunction appears to play a critical role in imbalances of lipid metabolism, bioenergetics, and insulin responsiveness in podocytes." (PMID 36641502, 2023). "Regarding utilization of diabetes technology, 56.0% of the study population used insulin pump therapy, and 29.4% used Real-Time Continuous Glucose Monitoring (rtCGM); 27.3% used both insulin pump and rtCGM." (PMID 37029362, 2023). "The researchers concluded that chromium intake plays a positive role for patients with diabetes, leading to improved insulin sensitivity and reduced blood sugar levels following treatment." (PMID 38024820, 2023). "This study was conducted only on a conveniently selected number of patients, which makes it difficult to generalize about both the practice and quality of life of all the diabetes patients treated with insulin." (PMID 37143082, 2023). "Insulin resistance which is defined as decreased biological response to insulin is common in prediabetic state and type 2 diabetes mellitus." (PMID 36873578, 2023). "The study objective is to determine whether daily administration of oral insulin from 4 months to 7 months until the age of 3 years old to children with elevated genetic risk for T1D reduces the cumulative incidence of β-cell autoantibodies and diabetes in childhood." (PMID 37297566, 2023). "Overall, DG plays a key role in regulating hepatic insulin sensitivity, especially during the pathophysiological processes of obesity, diabetes, and non-alcoholic fatty liver disease." (PMID 37124226, 2023). "Diabetes is a chronic, progressive disorder characterised by raised blood glucose levels due to insufficient production of the hormone insulin or decreased effectiveness of the insulin that the body produces." (PMID 37686786, 2023). "This review article will discuss the pathophysiological effects of gut microbiota in diabetes management and the impact of various gut biodiversity therapeutics that can aid in reversing insulin sensitivity." (PMID 37554593, 2023). "On the other hand, the DR1 subgroup had significantly higher mean age, systolic blood pressure (SBP), diastolic blood pressure (DBP), HDL, duration of diabetes, and insulin usage rate compared to DR0 (all p < 0.05)." (PMID 38174078, 2023). "Meanwhile, significant associations are detected between SNAP25 polymprphism rs363050 and increasing fasting glucose, HbA1c, and lower insulin in type 2 diabetes mellitus (T2DM) patients." (PMID 38371897, 2023). "Diabetes mellitus is a chronic metabolic disease characterized by decreasing insulin secretion or due to reduction insulin sensitivity of the cell of the body cell." (PMID 36604654, 2023). "Diabetes is a metabolic disease mainly manifesting through chronic hyperglycemia, resulting from impairment in insulin secretion and/or insulin action, with severe consequences." (PMID 38202328, 2023). "Considering pregnancy itself is an insulin-resistant state and GH is a potent insulin antagonist, acromegalic women in pregnancy are more likely to develop gestational glucose intolerance or diabetes mellitus." (PMID 37161564, 2023). "By addressing these specific areas of distress, the DSI scale can be used to improve patient comfort, adherence to insulin therapy, and ultimately achieve better diabetes management outcomes." (PMID 37474582, 2023). "Diabetes is a chronic condition characterized by elevated blood sugar levels due to insufficient insulin production or the body’s inability to use insulin effectively." (PMID 37600709, 2023). "The literature identifies that repeated use of insulin syringes and needles by patients living with diabetes is a common practice particularly in resource-limited countries." (PMID 37828591, 2023).
diabetes (continued). "In particular, patients below an age of 50y that received insulin prescriptions (ATC codes starting with A10A) were excluded in the LEICON dataset due to the higher likelihood of type 1 diabetes in younger diabetes patients." (PMID 37248318, 2023). "The higher prevalence of diabetes in PA can be explained by impaired pancreatic insulin secretion and reduced insulin sensitivity in the setting of high levels of aldosterone." (PMID 37305032, 2023). "Diabetes mellitus (DM) is a metabolic syndrome which is characterized by hyperglycemia that develops as a result of lack or deficit of insulin secretion or sometimes resistance to its function." (PMID 37316565, 2023). "Islets proteomics demonstrated that DFEs in the OI vs. STZ groups were significantly enriched in diabetes, insulin secretion, insulin resistance, and in the HIF1-α, mTOR, and MAPK signaling pathways." (PMID 36918798, 2023). "Patients initiating dapagliflozin were younger, with longer duration of diabetes, worse glycaemic, and blood pressure control and with higher prevalence of microvascular complications and use of insulin." (PMID 36624223, 2023). "Diabetes is a metabolic disorder characterized by high plasma glucose levels and can be classified as type I or type II (insulin-dependent or non-insulin-dependent, respectively)." (PMID 37298999, 2023). "Diabetes mellitus is a metabolic disorder characterized by hyperglycemia due to impaired insulin secretion, insulin resistance, or both." (PMID 37755075, 2023). "Diabetes mellitus is a pathologic condition characterized by a prolonged elevation of blood glucose due to insufficient insulin or insulin resistance." (PMID 36251044, 2023). "The guidelines further suggest that the choice of insulin should be individualized, considering the clinical status of patients with type 2 diabetes mellitus." (PMID 36650625, 2023). "We also present two patients who underwent a successful switch from insulin to oral glucose-lowering agents years after the diagnosis of diabetes." (PMID 36418577, 2023). "It will also be the first study to explore attitudes towards insulin patch pump use from healthcare professionals, highlighting a need for more research regarding clinician attitudes towards diabetes technologies." (PMID 37814352, 2023). "In a mouse model of streptozotocin-induced diabetes, the combination of Astragalus polysaccharides and Astragalus flavonoids significantly improved the function of insulin and thus exerted an anti-diabetic effect." (PMID 36985705, 2023). "Patients with diabetes have indicated that reducing the number of injections and administering insulin at convenient times can improve adherence." (PMID 37240580, 2023). "The persons with diabetes receiving insulin need to have regular meals to accompany the taking of their drugs." (PMID 37815062, 2023). "A guide to insulin treated diabetes and driving (INF294).Driver & Vehicle Licensing Agency; first published 2013." (PMID 37101052, 2023). "Diabetes results when our body is unable to make insulin or is unable to use the insulin produced by our body." (PMID 37958014, 2023). "Fasting blood glucose levels reflect the function of pancreatic islet beta cells, generally indicating the secretion function of basal insulin, which is the most commonly used index for detecting diabetes." (PMID 37415183, 2023). "In response to the impaired expandability of adipose tissue, excess lipids accumulate in skeletal muscle and result in insulin resistance in skeletal muscle, which is a major feature of type 2 diabetes mellitus and obesity." (PMID 38134035, 2023). "Five days after successful induction of STZ diabetes, rats were injected subcutaneously with diluted human insulin (Humulin R), followed by blood sampling for plasma insulin concentration over a two-hour period." (PMID 37384782, 2023).
diabetes (continued). "FOXO1 is a nuclear transcription factor whose expression can be induced by the presence of insulin; therefore, it can be overexpressed in skeletal muscles in energy-deprived states such as diabetes and is a key target of the PI3K/Akt signalling pathway." (PMID 37373351, 2023). "Diabetes mellitus is a chronic metabolic disorder characterised by the inability of the β-cells of the pancreas to produce enough insulin." (PMID 37504117, 2023). "Nevertheless, the risk for hypoglycaemia in patients with diabetes that experience AKI while hospitalized in general medical wards is still undefined and adjusted protocols for insulin dosing during hospitalization and after discharge are lacking." (PMID 37173530, 2023). "While conventional methods for measuring insulin in the clinic are sensitive and robust, point-of-care testing methods are urgently needed to improve the outlook for patients with diabetes." (PMID 37504117, 2023). "A century ago, the Nobel Prize in Physiology or Medicine was awarded jointly to Frederick Grant Banting and John James Rickard Macleod for the discovery of insulin and its relationship with diabetes." (PMID 37504117, 2023). "His sister developed convulsions and hypoglycemic coma at 5 months, and at 6 months was diagnosed with diabetes and received insulin for a few days before being transferred to SU treatment." (PMID 36398453, 2023). "Insulin therapy was required for glycemic control in 29 of 31 women with pre-existing diabetes, with a duration of 6.5 (IQR 3.0-13.5) years." (PMID 38047210, 2023). "Another relevant clinical mechanism impairing weight reduction is the use of obesogenic anti-diabetes medications such as insulin, sulfonylureas, meglitinides, and thiazolidinediones." (PMID 37990681, 2023). "Our study reveals an inhibitory effect of insulin or Mg2+ supplement on the inflammatory response of COX-2 that is probably triggered by PARs upregulation in diabetes." (PMID 37228689, 2023). "Most of the patients with diabetes were treated only with oral antidiabetics, and 2.5% were under insulin." (PMID 36921131, 2023). "Regarding CGC, a large prospective cohort study (NIH-AARP Diet and Health study) has previously shown a positive association between self-reported diabetes and CGC but there is little data on insulin and CGC." (PMID 37455285, 2023). "Firstly, a substantial proportion of the selected T2D population in our study was managed using insulin or diabetes-related medications, potentially influencing the baseline HbA1c levels." (PMID 37644580, 2023). "The antidiabetic regimen was switched to GLP-1 RA plus BI to replace previous treatment with premixed insulin in type 2 diabetes mellitus subjects." (PMID 36897731, 2023). "Fibroblast growth factor 21 has been suggested as a promising new drug for treating diabetes and obesity thanks to its multiple metabolic-regulating functions, such as enhancing insulin sensitivity and increasing energy expenditure." (PMID 38116563, 2023). "The role of serum adiponectin and serum resistin as a glucose metabolism regulator in diabetes is discoursed and it is found that biochanin-A improved adiponectin release and augments insulin activity." (PMID 38106650, 2023). "Intensive insulin treatment in newly diagnosed diabetes patients has proven its worth in terms of remission." (PMID 38094528, 2023). "There was a shift from the use of OADs towards the introduction of insulin as the need for injectables is common in people with longer duration of diabetes." (PMID 36722454, 2023). "Insufficient G6PDH activity can lead to cell growth arrest, impaired embryonic development, as well as a reduction in insulin sensitivity, inflammation, diabetes, and hypertension." (PMID 38046951, 2023). "The reduction of TG with insulin in HTG-AP was first described by Bagdade in 1967 in a patient with deranged diabetes." (PMID 37789261, 2023).
diabetes (continued). "Current treatment strategies, including exogenous insulin administration and islet transplantation, come with a myriad of complications, hindering them being an ideal end-point solution to treat diabetes." (PMID 37371672, 2023). "Factors that significantly increased the likelihood of being in the FFR- | iFR/RFR+ group are the treatment of diabetes mellitus with insulin and a low eGFR." (PMID 36826530, 2023). "Compared with MET monotherapy, exenatide monotherapy or in combination with MET achieve a higher rate of diabetes remission in PCOS patients by increasing insulin secretion after meals." (PMID 37383395, 2023). "By improving insulin sensitivity, physical exercise can reduce the reliance on medication or insulin therapy in managing diabetes." (PMID 37998439, 2023). "In order to boost insulin release from pancreatic cells, the conventional medication Glibenclamide has been used to treat diabetes for several decades." (PMID 38053673, 2023). "Treatment with insulin or two doses of kiwi extract also significantly reduced lipid profile markers related to diabetes (p < 0.01)." (PMID 37762060, 2023). "Consistently, metabolic stress has been reported to elevate oxidative stress through the production of ROS, which dampens insulin release and insulin action during diabetes." (PMID 36935456, 2023). "Two transwomen had a diagnosis of type 1 diabetes mellitus: in one of them the insulin requirements remained stable while the other one required a doubling of the total insulin dose (from 50 to 97 UI per day)." (PMID 37834785, 2023). "There is a significant need for therapeutic agents that enhance insulin secretion and improve insulin sensitivity in the treatment of diabetes." (PMID 38125492, 2023). "Given the nature of insulin-treated diabetes, a deliberate decision was made to opt for a smaller, more manageable sample size, allowing for a thorough investigation within the constraints of available resources." (PMID 38077677, 2023). "This can occur in genetic glycogen storage disease or acquired conditions with insulin dysregulation such as diabetes mellitus and non-alcoholic fatty liver disease or medication effects." (PMID 37047105, 2023). "There are some similarities in changes of microflora from insulin-treated patients comorbid with diabetes and NASH." (PMID 37852976, 2023). "Islet cell loss due to extensive pancreatic necrosis, persistent inflammatory response, and disruption of the insulin-incretin axis have been suggested as the pathophysiology of diabetes following AP." (PMID 37208706, 2023). "GSH, whose levels are low in diabetes, is also important for coupling glucose to the stimulation of insulin secretion through the isocitrate-to-SUMO-specific peptidase 1 pathway." (PMID 36137277, 2023). "Diabetes mellitus is metabolic disorder disease characterized by increasing blood glucose level in the body resulting from either defect insulin secretion, insulin action, or both." (PMID 37643198, 2023). "Insulin stimulates Lpl expression and Lpl activity is lower in patients with diabetes, which in turn impair lipoproteins’ metabolism, leading to hyperglyceridemia." (PMID 37337262, 2023). "It plays a crucial role in the regulation of glucose homeostasis, insulin secretion, and the pathogenesis of diabetes mellitus." (PMID 37601108, 2023). "Diabetes mellitus is a group of metabolic disorders characterized by long-term hyperglycemia resulting from defects in insulin action, insulin secretion, or both." (PMID 36647067, 2023). "In diabetes, metabolic disfunction impairs glucose sensing, compromises mitochondrial regulation, lowers ATP production and ultimately, impacts insulin secretion." (PMID 37929027, 2023). "We know that the quality and quantity of foods have a pivotal role in order to regulate the levels of postprandial blood glucose and daily insulin requirements in patients with diabetes." (PMID 37630698, 2023).
diabetes (continued). "Diabetes mellitus is a chronic metabolic disorder characterized by high blood glucose levels resulting from insulin resistance or impaired insulin secretion, or both." (PMID 37280499, 2023). "When pancreatic beta cells fail to secrete enough insulin to overcome insulin resistance, this results in the inability to maintain glucose homeostasis and the development of type 2 diabetes mellitus (T2DM)." (PMID 38066741, 2023). "Since the first description of GOAT in 2010, GOAT inhibitors have become a promising therapeutic strategy in the treatment of obesity and diabetes via their ability to increase insulin response and reduce ghrelin activity." (PMID 36837889, 2023). "Diabetes mellitus (DM), characterised by elevated levels of blood glucose resulting from defective insulin secretion and/or action, has emerged to become a major global public health problem." (PMID 36777336, 2023). "We clearly observed that the amount of mouse insulin was decreased in mice with STZ-induced diabetes compared to that in the healthy mice (Ctrl group)." (PMID 37644502, 2023). "Unique challenges also exist for people living with diabetes regarding insulin sensitivity and medication, including insulin, that can affect weight gain." (PMID 37903137, 2023). "With the help of continuous glucose monitors, glucose variability is one of many tools to investigate the impact of changes in a patient’s diabetes care such as insulin adjustments and carbohydrate ratios." (PMID 36674378, 2023). "These biosensors have the potential to provide a seamless and automated solution for individuals with diabetes, allowing for continuous monitoring of glucose levels and the automatic administration of insulin when needed." (PMID 38239544, 2023). "Continuous subcutaneous insulin infusion (CSII) using an insulin pump is one of the most notable advancements in diabetes technology." (PMID 38371896, 2023). "In our patients, the average ± SD age was 70.4 ± 9.2 years, diabetes duration 17.4 ± 7.1 years, 51% were females, average daily insulin dose was 46.4 units (80% received biphasic aspart)." (PMID 36882852, 2023). "Higher FBG level is due to an increase in glucagon to insulin ratio as seen in diabetes, where the liver is involved in excess glycogen breakdown and gluconeogenesis." (PMID 38124783, 2023). "We present the case of a 58-year-old Hui woman with a history of type 2 diabetes mellitus with nephropathy and heart disease for which she was treated with metformin, insulin, and heart medications." (PMID 37993970, 2023). "For example, continuous wearable glucose monitors and insulin pumps have been developed to facilitate ease of monitoring and administration of insulin among patients with diabetes." (PMID 37695663, 2023). "The results showed that the flavonoids in mulberry leaves reduced the superoxide dismutase (SOD)-peroxidase (CAT) ratio, decreased metalloproteinase-2 activity, increased blood insulin levels and reduced hyperglycaemia-induced diabetes." (PMID 37089923, 2023). "Multiple studies on the effect of curcumin, a natural polyphenolic compound derived from Curcuma longa, demonstrate pluripotent effects on oxidative stress, insulin sensitivity and cardiovascular health in people with diabetes." (PMID 37237992, 2023). "Type 2 diabetes mellitus is a multifactorial metabolic condition marked by persistent hyperglycemia brought on by reduced insulin sensitivity or generation." (PMID 37554894, 2023). "Although pioglitazone has the risk of causing water and sodium retention, however, the higher risk of edema in the diabetes group is more likely due to the combination of insulin use in most diabetes patients." (PMID 37065735, 2023). "Those PPAR-γ ligands, which are called insulin-sensitizing drugs, have been recommended as antidiabetic agents for type 2 diabetes mellitus." (PMID 37111279, 2023).